RN7SL418P (RNA, 7SL, cytoplasmic 418, pseudogene)
Gene: Miscellaneous RNA gene on chromosome 3 (69,769,487 to 69,769,773, reverse strand). Ensembl gene ENSG00000241665.
Homologues: Orthologues: chimpanzee Metazoa_SRP (99% identical), macaque Metazoa_SRP (90% identical). Paralogues in human: RN7SL1 (84% identical), RN7SL2 (83% identical), RN7SL3 (83% identical), RN7SL14P (82% identical), RN7SL230P (82% identical), RN7SL47P (81% identical), RN7SL91P (81% identical), RN7SL444P (80% identical), RN7SL45P (80% identical), RN7SL655P (80% identical), RN7SL865P (80% identical), RN7SL187P (79% identical), and 705 more.